CDK4 (cyclin dependent kinase 4)
Diseases named in the same sentence as CDK4 in open-access papers (continued):
Sharing a sentence is not in itself a finding about the gene and the disease.
breast cancer (continued). "The iDFS improvement with CDK4/6 inhibitors becomes more evident over time, suggesting broader benefits and enhanced long-term efficacy for HR+, HER2-breast cancer patients especially with N0 or Stage II." (PMID 40717978, 2025). "The characterization of these cells and models of resistance post CDK4/6 inhibitor + ET treatment highlight the potential for novel therapeutic approaches to overcome resistance to CDK4/6i + ET in HR+, HER2− breast cancer." (PMID 40141282, 2025). "Although some studies have indicated that CDK4/6 inhibitors are beneficial for the progression-free survival (PFS) and overall survival (OS) in breast cancer, evidence regarding the assessment of clinical response remains insufficient." (PMID 40922517, 2025). "Abemaciclib, a CDK4/6 inhibitor, is well-established for treating hormone receptor-positive and HER2-negative (HR+/HER2−) human breast cancer by inducing G1 cell cycle arrest." (PMID 40642276, 2025). "In patients with breast cancer (n = 75,553), the HRs for ATE were 0.81 (95% CI: 0.64–1.04) with HER2-targeted therapy (n = 9246) and 0.73 (95% CI: 0.30–1.76) with CDK4/6-inhibitors (n = 1800)." (PMID 40896464, 2025). "CDK4/6 inhibitors dramatically change the treatment landscape for patients with HR-positive, HER2-negative advanced breast cancer." (PMID 40421216, 2025). "At last, our data point to a common mechanism used by MDA-MB-468 and HCC1143 basal-like breast cancer cell lines, involving Wnt/ERK/CDK4/6 activation leading to E/M or CSC maintenance and self-renewal combined with inhibition of differentiation." (PMID 40764669, 2025). "In the PALOMA-2, MONALEESA-2, MONARCH-3, and MONALEESA-7 phase III trials, the addition of CDK4/6is (palbociclib, ribociclib, abemaciclib) to ET significantly improved PFS when used as first-line therapy in both pre- and postmenopausal breast cancer patients." (PMID 40244377, 2025). "The androgen receptor of prostate cancer is similar to the estrogen receptor in breast cancer, which may activate the cyclin D-CDK4/6, driving the proliferation of prostate cancer and resistance to hormone manipulation.Therefore, this has stimulated the search for CDK4/6 inhibitors." (PMID 41200193, 2025). "Upregulation of anti-apoptotic proteins Bcl-2, Bcl-xl, and Mcl-1 in endocrine therapy-resistant, CDK4/6i-resistant, and HER2 TKI-resistant breast cancer cell lines validates this theory." (PMID 40949156, 2025). "This is primarily due to the reduction in expression of CDK2, CDK4, CDK6, and Akt proteins, which enhances the sensitivity of resistant breast cancer cells to tamoxifen." (PMID 40283888, 2025). "We also analyzed our own ER+ breast cancer patient cohort (NCT04526587), comparing the expression of CCNE1 and CDKN2A before and following progression on CDK4/6 inhibitor-based treatment." (PMID 39924553, 2025). "CDK4/6 inhibitors (CDK4/6i) represent the first-line therapy approach of choice for patients with hormone receptor-positive, HER2-negative advanced breast cancer (HR + /HER-ABC)." (PMID 39373732, 2025). "Currently, three orally administered CDK4/6 inhibitors abemaciclib, palbociclib and ribociclib have received FDA approval for the treatment of HR+/HER2− breast cancer patients." (PMID 39968498, 2025). "For example, a combinatorial trial with the CDK4/6 inhibitor abemaciclib and the autophagy inhibitor hydroxychloroquine (NCT04523857) has been designed to eliminate dormant breast cancer cells." (PMID 41453945, 2025). "The efficacy of CDK4/6is in the adjuvant treatment of HR+/HER2- ABC has been established, but in the clinic, more than 90% of breast cancer patients are diagnosed at an early stage." (PMID 40134916, 2025).
breast cancer (continued). "The gene expressions of CDK4, CDK6, TGF-β, and NF-κβ were significantly reduced by abemaciclib in breast cancer cell lines MCF-7 and MDA-MB-231 compared to untreated cells of each cell line." (PMID 40035822, 2025). "Therefore, the development of inhibitors against CDK4/6, the development of drug candidates targeting lncRNAs and the screening of natural compounds for adjuvant therapy are being anticipated as new strategies for the treatment of breast cancer using the cell cycle as a supportive point." (PMID 40093330, 2025). "This retrospective study evaluates the safety of combining CDK4/6 inhibitors with palliative radiotherapy in metastatic hormone receptor-positive, HER2-negative breast cancer." (PMID 39941794, 2025). "In this study, we aimed to investigate the effects of androgen receptor (AR) expression, as well as the AR/ER and AR/PR ratios, on responses to CDK4/6 inhibitor treatment and progression-free survival (PFS) in breast cancer patients." (PMID 40870508, 2025). "The present study confirms that CDK4/6 inhibitors provide clinical benefits, including OS benefit consistent with PFS, to HR+/HER2- advanced breast cancer patients." (PMID 40740245, 2025). "The PALOMA trials investigated the role of palbociclib, a selective CDK4/6 inhibitor, in combination with endocrine therapy for hormone-receptor-positive, HER2-negative breast cancer." (PMID 40731911, 2025). "Currently, there are several confirmed regimens for improving DFS in patients with breast cancer, including prolonged tamoxifen duration, switching to AIs, addition of OFS and addition of CDK4/6 inhibitor abemacilib." (PMID 40050768, 2025). "The combination of CDK4/6 inhibition with estrogen receptor antagonists has become a standard treatment for both early and advanced ER+/HER2− breast cancer patients." (PMID 40563591, 2025). "Cyclin-dependent kinase 4/6 inhibitors (CDK4/6i), utilized in breast cancer treatment, also exert considerable influence on tumor-cell PD-L1 regulation and the immune microenvironment." (PMID 41550427, 2025). "Consistently, ERK/CDK4/6 drug perturbation in E/M cells suppressed FOXC2/p63, FOXM1, self-renewal, organoid formation and mammary tumour growth via epithelial differentiation." (PMID 40764669, 2025). "The cyclin-dependent kinase 4/6 inhibitor (CDK4/6i) ribociclib, abemaciclib, and palbociclib have transformed outcomes in patients with ER+ /HER2 − advanced breast cancer (BC)." (PMID 40764324, 2025). "The MONARCH-1 trial studied abemaciclib, a CDK4/6 inhibitor, in 132 patients with refractory HR+/HER2− breast cancer and demonstrated an ORR of 19.7%, mPFS of 6.0 months, and mOS of 17.7 months." (PMID 39330025, 2024). "Considering the effectiveness of CDK4/6i in HR + /HER2- MBC treatment, these drugs are now under investigation in various breast cancer subtypes and different clinical scenarios." (PMID 38409585, 2024). "First of all, to our knowledge, it is the first comparative comprehensive pharmacoeconomic evaluation for the three CDK4/6 inhibitors and letrozole monotherapy in the first-line use of HR+/HER2- advanced breast cancer." (PMID 39114308, 2024). "CDK4/6i, including Palbo, ribociclib, and abemaciclib, have revolutionized the treatment landscape for HR+, HER2− advanced breast cancer." (PMID 39766060, 2024). "Among this series, compound St.29 showed a potent inhibitory effect against MDA-MB-231 and MCF-7 breast cancer cell lines with low IC50 values, as well as a selective inhibitory effect against CDK4/6." (PMID 39404419, 2024). "Subsequently, correlation analysis of breast cancer in TCGA indicated that the expression of CARM1 is positively correlated with that of HIF1A and CDK4." (PMID 38476024, 2024). "In this study, we examined a mathematical model of breast cancer (BC) treatment that combines an oral oestrogen receptor inhibitor, AZD9496 with Palbociclib, a selective inhibitor of cyclin- dependent kinases CDK4 and CDK6." (PMID 38225243, 2024).
breast cancer (continued). "Treatment with a CDK4/6 inhibitor plus endocrine therapy is now the standard therapeutic regimen for hormone-positive, HER2-negative advanced breast cancer." (PMID 38622197, 2024). "A total of 20 randomized controlled trials (RCTs) were included in this study, investigating the effectiveness of four CDK4/6 inhibitors—Abemaciclib, Dalpiciclib, Ribociclib, and Palbociclib—when combined with ET for the treatment of HR+/HER2-breast cancer." (PMID 38832268, 2024). "Current studies highlight selective CDK4/6 inhibitors, like palbociclib or abemaciclib, as a very promising therapeutic option, since they were accepted by the FDA for advanced breast cancer treatment." (PMID 39598629, 2024). "This study aimed to evaluate the efficacy and safety of CDK4/6 inhibitors combined with endocrine therapy versus endocrine therapy alone in patients with HR+, HER2- early breast cancer." (PMID 39329126, 2024). "Extensive in vitro and in vivo studies have unequivocally revealed the significant growth-inhibitory effects of CDK4/6 inhibitors combined with endocrine therapy in HR+/HER2-0 and HR+/HER2-low breast cancer cell subtypes." (PMID 39730704, 2024). "CDK4/6 inhibitors have proven potent antitumor activity, for example, in estrogen/progesterone+/HER2− breast cancer patients." (PMID 39330025, 2024). "We show that although the proliferation of luminal breast cancers is initially CDK4/6-dependent, CDK2 activity can overcome persistent CDK4/6 inhibition, eventually restoring Rb phosphorylation to a level that facilitates cellular entry into S-phase." (PMID 38047585, 2024). "The efficacy of CDK4/6 inhibitors plus ET in hormone estrogen-positive, human epidermal growth factor 2-negative (HR+/HER2−) early-stage breast cancer (esBC) is still to be confirmed." (PMID 38793046, 2024). "There are three CDK4/6 inhibitors that are currently approved by the Food and Drug Administration (FDA) for the treatment of advanced breast cancer: palbociclib, ribociclib, and abemaciclib." (PMID 39114308, 2024). "This study aimed to use network meta-analysis to compare the efficacy and safety of CDK4/6 inhibitors combined with ET, providing a more evidence-based foundation for clinical drug selection in patients with HR+/HER2-breast cancer." (PMID 38832268, 2024). "Recent research has focused on selecting the most effective endocrine partner for CDK4/6i in postmenopausal women with endocrine-sensitive, HR + /HER2- advanced breast cancer." (PMID 38409585, 2024). "Strikingly, neratinib reversed the efficacy of CDK4/6 inhibitor and endocrine therapy by reducing HER2 mRNA stability in HR+/HER2-low breast cancer through the interaction of HER2 3’-UTR region with hsa-miR-23a-5p." (PMID 39730704, 2024). "In conclusion, this study revealed that CDK4/6 inhibitors can enhance the efficacy of adjuvant and neoadjuvant therapy in HR+/HER2- early breast cancer patients." (PMID 39329126, 2024). "Collectively, HER2 knockdown significantly induced G1 phase arrest, decreased the expression of Cyclin D1 and CDK4, and enhanced the inhibitory effect of CDK4/6 inhibitor combined with endocrine therapy on HR+/HER2-low breast cancer cells." (PMID 39730704, 2024). "TRAIL-inducing compound 10 (Tic 10) can reduce the expression of cell division protein kinase 4 (CDK4) by activating FOXO3a, thereby reversing the resistance of the breast cancer T47D/5-Fu cells to 5-fluorouracil in vitro and in vivo." (PMID 38505423, 2024). "In this study, the treatment of breast cancer involving a combination of two drugs was investigated: the oral estrogen receptor inhibitor AZD9496 and the CDK4/6 protein inhibitor Palbociclib." (PMID 39935852, 2024). "Next, to comprehensively evaluate the in vivo effect of the combination of neratinib with CDK4/6 inhibitor and endocrine therapy in HR+/HER2-low breast cancer, a xenograft mouse model was established with human HR+/HER2-low breast cancer cells." (PMID 39730704, 2024).
breast cancer (continued). "Since 2018, CDK4/6 inhibitors (CDK4/6i) (e.g., palbociclib, ribociclib or abemaciclib) combined to endocrine therapy became the backbone of the treatment of HR + /HER2− breast cancer." (PMID 39090361, 2024). "PARP inhibitors like Olaparib, CDK4/6 inhibitors such as palbociclib, abemaciclib, and ribociclib have received FDA approval for treating breast cancer." (PMID 39902127, 2024). "Molecular targeted therapies have attracted attention, with anti-HER2 agents, CDK4/6 inhibitors, PARP inhibitors, and mTOR inhibitors being used to treat breast cancer." (PMID 39273689, 2024). "For breast cancer, we chose the MCF7 cell line, which models triple-negative breast cancer (TNBC), despite CDK4/6 inhibitors typically targeting HR+ breast cancer." (PMID 39000513, 2024). "This study revealed that the triad combination of neratinib, CDK4/6 inhibitor, and endocrine therapy exerted superior suppression of HR+/HER2-low breast cancer growth." (PMID 39730704, 2024). "At present, three CDK4/6 inhibitors (CDK4/6i) Palbociclib, Ribociclib and Abemaciclib are FDA-approved and are further evaluated in clinical trials in several cancers, including breast cancer, non-small and small cell lung cancer, and prostate cancer." (PMID 39090086, 2024). "From 2015 to 2017, selective inhibitors targeting CDK4 and CDK6 gained US FDA approval for treating breast cancer, including palbociclib, abemaciclib, and ribociclib." (PMID 39184861, 2024). "Treatment options for advanced breast cancer rely on chemotherapy, targeted therapy (e.g. HER2-directed therapy, Cyclin-dependent Kinase 4/6 (CDK4/6) inhibitors, antibody-drug conjugates), endocrine therapy, immunotherapy, or combinations of these therapies." (PMID 38912829, 2024). "For instance, in breast cancer, the FDA-approved CDK4/6 inhibitors, such as palbociclib, have demonstrated substantial clinical benefits by inhibiting the activity of CCND1-CDK4 complex and arresting tumor growth." (PMID 38957406, 2024). "The combination of cyclin-dependent kinases 4/6 (CDK4/6) inhibitors and endocrine therapy is the standard treatment for patients with hormone receptor-positive (HR+)/HER2-negative (HER2-) advanced breast cancer." (PMID 39329126, 2024). "As a game changer in ER positive advanced breast cancer, the cyclin-dependent kinase 4 and 6 (CDK4/6) inhibitors such as palbociclib, ribociclib, and abemaciclib, are currently treated for patients with ER positive and HER2 breast cancer." (PMID 38393465, 2024). "This study newly found that the HER2 pathway is crucial in modulating the response to CDK4/6 inhibitors and endocrine therapy in HR+/HER2-low breast cancer." (PMID 39730704, 2024). "In the last few years, three CDK4/6 inhibitors (i.e., palbociclib, ribociclib, abemaciclib) have been approved for the treatment of patients with metastatic HR+/HER2- breast cancer in combination with endocrine therapy." (PMID 38992220, 2024). "These novel endocrine agents have shown activity after fulvestrant and CDK4/6 inhibitors, and on mutant ESR1 in breast cancer." (PMID 38791941, 2024). "Another study found high expression of TROJAN in ER+ breast cancer, which by inhibiting cyclin-dependent kinase 2(CDK2) activity, reversed resistance to CDK4/6 inhibitors." (PMID 39253075, 2024). "Palbociclib was the first FDA approved CDK4/6 inhibitor and highly efficacious in the treatment of HR+/HER2- breast cancers, followed by the structurally related molecules ribociclib and abemaciclib." (PMID 38562687, 2024). "Three CDK4/6 inhibitors, palbociclib, ribociclib, and abemaciclib, have been widely used as first-line treatments for patients with HR-positive/HER2-negative breast cancer." (PMID 39011505, 2024). "Compared with that in normal tissues, the expression of CDK4, HIF1A, and MALAT1 were upregulated in the breast cancer samples, which was consistent with the results of CARM1." (PMID 38476024, 2024).
breast cancer (continued). "Preclinical data support the notion that CDK4/6i can overcome resistance to HER2-targeted therapies, thereby delaying recurrence in HER2+ breast cancer patients." (PMID 38409585, 2024). "The strongest evidence demonstrated that CDK4/6 inhibitor combined with ET significantly improved progression-free survival (PFS), overall survival (OS) in advanced breast cancer (ABC)." (PMID 38240835, 2024). "Men with ER-positive/HER2-negative breast cancer had more frequent alterations in GATA3, MDM2, CDK4, BRCA2 genes as compared with FBC patients of the same subtype." (PMID 39049124, 2024). "The overexpression of KNSTRN enhanced the expression of key cell cycle regulators, including CDK4, CDK6, and cyclin D3, thereby accelerating the G1/S phase transition and leading to aberrant proliferation of breast cancer cells." (PMID 38198023, 2024). "Recent evidence suggests that CDK4/6i provide a PFS benefit, particularly in breast cancer patients with bone-only disease, leading to extended disease control and improved survival." (PMID 38409585, 2024). "Inhibition of MAP3K3 by shRNA transduction or ponatinib treatment suppressed YAP-dependent resistance to the CDK4/6 inhibitor palbociclib, which is a mainstay targeted therapy for hormone-positive HER2-negative breast cancers." (PMID 38622197, 2024). "HR+/HER2-low breast cancer is a significant subgroup of conventional HR+/HER2-negative breast cancer, and combination of CDK4/6 inhibitor and endocrine therapy is the standard first-line and second-line treatments for advanced HR+/HER2-low breast cancer." (PMID 39730704, 2024). "For instance, three drugs including Palbociclib, Ribociclib, and Abemaciclib are selective CDK4/6 inhibitors and are used for treating HER2+/HR advanced breast cancer and have been approved by the FDA in 20174." (PMID 38961127, 2024). "Exploiting this PI3K vulnerability has proven to be highly effective, making triple combination therapy (a CDK4/6 inhibitor, a PI3K inhibitor, and endocrine therapy) one of the most potent treatment regimens for breast cancer patients in clinical settings." (PMID 39501277, 2024). "Numerous clinical studies have demonstrated similar efficacy of the three CDK4/6 inhibitors in combination with ET, all of which significantly prolong the PFS and ORR of HR+/HER2-breast cancer patients." (PMID 38832268, 2024). "There is a growing interest in CDK4/6 inhibitors for the treatment of HR‐positive, HER2‐positive breast cancer." (PMID 38469548, 2024). "In summary, we studied the effects of CDK4/6 inhibitor in combination with endocrine therapy in HR+/HER2-low and HR+/HER2-0 breast cancer cell subtypes both in vitro and in vivo." (PMID 39730704, 2024). "Palbociclib (PALBO) is a selective cyclin-dependent kinase 4/6 (CDK4/6) inhibitor that has been approved for advanced hormone receptor-positive and HER2-negative breast cancer treatment." (PMID 38786063, 2024). "Abemaciclib (Abe) is one of the most potent and selective CDK4/6 inhibitors and is FDA-approved for breast cancer." (PMID 39123441, 2024). "The biological changes that occur during CDK4/6 inhibition were assessed in T47D (HR+/HER2-/HER2-enriched), MCF7 (HR+/HER2-/Luminal B), and BT474 (HR+/HER2+ /HER2-enriched) breast cancer cell lines." (PMID 38992220, 2024). "Certain targets were enriched in specific cancer types as expected based on the clinical treatment landscape or tumor biology (eg, EGFR, MET, ROS1, MET, and ALK in NSCLC; or ERBB2, CDK4, CDK6, aromatase, and ER in breast cancer)." (PMID 37682776, 2024). "The monarcHER and PATRIICA trials have revealed a synergistic benefit in the co-inhibition of CDK4/6 and HER2 for the treatment of advanced HR + /HER2+ breast cancer." (PMID 38409585, 2024). "In mouse models of breast cancer, the combination of ARV-471 with the CDK4/6 inhibitor Palbociclib significantly suppressed tumor progression." (PMID 39315102, 2024).